PIM1 (Pim-1 proto-oncogene, serine/threonine kinase)
Diseases named in the same sentence as PIM1 in open-access papers (continued):
Sharing a sentence is not in itself a finding about the gene and the disease.
Hyperglycemia (3 papers, 2017 to 2023). An increased concentration of glucose in the blood. "In addition to PAH, exposure to high glucose in culture, similar to those experienced in hyperglycaemia and diabetes, has also been shown to induce Pim-1 mRNA and protein expression in VSMCs." (PMID 37511341, 2023). "Pim-1 and proliferating cell nuclear antigen (PCNA) expression levels in arterial samples from streptozotocin-induced hyperglycemia rats were increased, compared with their weak expression in normoglycemic groups." (PMID 29179437, 2017). "Whilst the authors demonstrated that this was due to the increased expression of SDF-1α, Pim-1 has been shown to positively regulate CXCR4 signalling in other cell types, indicating the potential to target the kinase to prevent CXCR4-mediated VSMC proliferation during hyperglycaemia." (PMID 37511341, 2023).
myocardial infarction (3 papers, 2017 to 2020). Gross necrosis of the myocardium, as a result of interruption of the blood supply to the area, as in coronary thrombosis. "In a myocardial infarction swine model, the overexpression of PIM1 had therapeutic engraftment effects in hCPCs48." (PMID 32273566, 2020). "Myocardial infarction injury, as represented by decreased infarct size and improved contractile performance, was mediated by cardiac specific overexpression of human PIM1 in transgenic mice." (PMID 32878131, 2020). "PIM1-MC showed moderate cardioprotection short-term after myocardial infarction by EF compared to gfp-MC or the PBS group." (PMID 28323876, 2017). "Modification of cardiac progenitor cells (CPCs) or cardiomyocytes with PIM1 using a lentivirus-based delivery method showed long-term improved cardiac function after myocardial infarction (MI)." (PMID 28323876, 2017).
osteoarthritis (3 papers, 2019 to 2023). A noninflammatory degenerative joint disease occurring chiefly in older persons, characterized by degeneration of the articular cartilage, hypertrophy of bone at the margins and changes in the synovial membrane. "A recent study suggests that PIM1-quercetin docking may play an important role in the treatment of osteoarthritis." (PMID 36968004, 2022). "However, few literature works studied the correlation between PIM1 and osteoarthritis." (PMID 31998395, 2019). "After validation by GSE55457, PIM1, CY1B1, and HSPA2 were considered as the key proteins during the treatment of osteoarthritis by quercetin." (PMID 31998395, 2019). "By validation of DEGs of GSE55457, three common proteins, PIM1, CYP1B1, and HSPA2, were considered as the key targeted proteins of the quercetin during the treatment of osteoarthritis by Achyranthes bidentata." (PMID 31998395, 2019). "In conclusion, the docking of PIM1-quercetin, CYP1B1-quercetin, and HSPA2-quercetin may play important roles during the treatment of osteoarthritis by Achyranthes bidentata." (PMID 31998395, 2019). "The docking of PIM1-quercetin, CYP1B1-quercetin, and HSPA2-quercetin may play important roles during the treatment of osteoarthritis by Achyranthes bidentata." (PMID 31998395, 2019).
osteosarcoma (3 papers, 2019 to 2023). A usually aggressive malignant bone-forming mesenchymal neoplasm, predominantly affecting adolescents and young adults. "Overexpressing PIM1 in the human osteosarcoma cell line U2-OS led to increased proliferation and motility, implying a more metastatic phenotype." (PMID 35892829, 2022). "PIM1 inhibition in osteosarcoma cells by siRNA or the PIM1 inhibitor, SMI-4a, led to increased apoptosis, and decreased proliferation and motility." (PMID 35892829, 2022). "The investigators ultimately showed that PIM1 expression independently predicted overall survival and disease-free survival in osteosarcoma." (PMID 35892829, 2022). "Narlik-Grassow similarly found that PIM1, but not PIM2 or PIM3, expression correlated with poorer prognosis in osteosarcoma." (PMID 35892829, 2022).
triple-negative breast carcinoma (3 papers, 2020 to 2025). An invasive breast carcinoma which is negative for expression of estrogen receptor (ER), progesterone receptor (PR), and human epidermal growth factor receptor 2 (HER2). "Both PIM1 knockdown and PIM1 inhibitors decrease proliferation in triple-negative breast cancer." (PMID 40018406, 2025).
(ZIKV) infection (2 papers, 2022 to 2024). "Thus, we speculated that the high expression level of PIM1 may have an important effect on fetal microcephaly caused by ZIKV infection in pregnant women." (PMID 39679197, 2024). "A previous report revealed that ZIKV infection can stimulate PIM1 kinase expression, and that PIM1 facilitates ZIKV replication by suppressing host cell type I IFN signaling activity." (PMID 39679197, 2024). "PIM1, a serine/threonine protein kinase widely involved in cell proliferation, survival, differentiation and apoptosis, was recently reported to be upregulated by Zika virus (ZIKV) infection." (PMID 39679197, 2024). "Notably, ZIKV infection upregulates PIM1 and exploits PIM1 to suppress type I IFN signaling activity." (PMID 39679197, 2024). "Besides, the overexpression of PIM1 could also significantly increase the protein level of prM under ZIKV infection." (PMID 39679197, 2024). "Recently, Zhou and colleagues demonstrated that ZIKV infection induces a time-dependent increase in PIM1 mRNA and protein and knockdown or inhibition of PIM1 isoform reduces ZIKV replication, providing further evidence that PIM kinases could be relevant factors in viral replication." (PMID 35216015, 2022).
Arthritis (2 papers, 2019 to 2022). Inflammation of a joint. "Further, kaempferol could effectively improve the symptoms of arthritis in mice and decrease the PIM1-mediated phosphorylation of S422 at Foxp3." (PMID 36248435, 2022).
atherosclerosis (2 papers, 2010 to 2025). A disease characterized by the build-up of fatty material and calcium deposition in the arterial wall resulting in partial or complete occlusion of the arterial lumen. "Furthermore, it was shown that Pim-1, a protooncogene that encodes a serine/threonine kinase, is also induced by ROS, and thus is likely involved in the progression of atherosclerosis." (PMID 20182627, 2010). "ApoE-/- C57 mice were injected recombinant adeno-associated virus serotype 9 through tail vein to explore the role of PIM1 in atherosclerosis." (PMID 39744686, 2025). "Endothelial cell-specific PIM1 knockdown negatively regulated atherosclerosis progression and the EndMT process." (PMID 39744686, 2025). "Taken together, ROS and subsequent activation of various stress signaling such as JNK and Pim-1 are involved in the progression of atherosclerosis." (PMID 20182627, 2010). "Although our study demonstrates that PIM1 promotes the phosphorylation of NDRG1, leading to its nuclear translocation and the subsequent progression of EndMT and atherosclerosis, it is important to note that other mechanisms by which NDRG1 promotes atherosclerosis progression still exist." (PMID 39744686, 2025).
breast tumor (2 papers, 2017 to 2024). "Interestingly, this subset with higher PIM1/2 expression has poor prognosis that is also observed in relapse and resistance to therapy, at least in breast tumors." (PMID 28938604, 2017). "We found 665 genes which expression significantly correlated with the expression of PIM1 and PIM2 in human breast tumors (Pearson r > 0,3), 296 that significantly correlated to PIMs in endometrial tumors (Pearson r > 0,3) and 6661 in ovarian tumors (Pearson r > 0,3)." (PMID 28938604, 2017). "Therefore, we applied a combination treatment strategy of PIM1 and autophagy inhibition using SMI-4a and Lys05 respectively, showed higher efficacy against cell viability of both these populations and further reduced breast tumor formation and metastasis." (PMID 38645153, 2024).
cardiomyopathy (2 papers, 2014 to 2023). A disease of the heart muscle or myocardium proper. "This suggests potential redundancy between the isoforms, with Pim-2 and -3 compensating for the loss of Pim-1 in basal conditions to prevent cardiomyopathy, with loss of cardiac Pim-1 associated with increased expression of Pim-2." (PMID 37511341, 2023). "We also demonstrate that early downregulation of pro-survival protein Pim-1 plays a major role in accelerating the progression of cardiomyopathy in female diabetics through upregulation of miR-1 and 208a." (PMID 24685144, 2014). "Interestingly, in contrast to findings identifying Pim-1 as a key mediator of cardiomyocyte function and survival, genetic deletion of Pim-1 in mice does not appear to lead to cardiomyopathy in basal conditions." (PMID 37511341, 2023).
CNS DLBCL (2 papers, 2022). "Although we established such a molecular classification for CNS DLBCL in present study, the underlying mechanism by which CD79B and PIM1 mutational status impact the outcome of primary CNS DLBCL after HD-MTX-based polychemotherapy remains unknown." (PMID 35223507, 2022). "Therefore, in terms of application, our data suggest that a new molecular classification based on the mutational status of CD79B and PIM1 could be used to predict patient outcomes in CNS DLBCL." (PMID 35223507, 2022). "In present study, we attempted to classify primary CNS DLBCLs into two biologically relevant subgroups based on the mutational status of CD79B and PIM1 by targeted exome sequencing covering 413 genes." (PMID 35223507, 2022). "CNS DLBCLs frequently harbored MYD88, CD79B and/or PIM1 mutations." (PMID 35223507, 2022). "CNS DLBCL patients without PIM1 and CD79B mutations had inferior long-term survival after HD-MTX-based chemoimmunotherapy in the present study, even though they were younger and had a lower MCD subtype." (PMID 35223507, 2022).
erythroleukemia (2 papers, 2014 to 2016). Acute erythroid leukemia characterised by the presence of at least 50% erythroid precursors and at least 20% myeloblasts in the bone marrow. "Indeed, the integration of the Friend murine leukemia virus (F-MuLV) into the pim1 locus was reported to induce erythroleukemia, and integrations into the c-myc and pim1 loci have been described in T-lymphoid leukemias." (PMID 24860787, 2014).
hypertrophy (2 papers, 2024 to 2025). Hypertrophy is the increase in the volume of an organ or tissue due to the enlargement of its component cells. "Another study demonstrated that Pim1 contributes to myocardial hypertrophy in mice after transverse aortic constriction." (PMID 39850120, 2025). "Theoretically, Pim3, which has a similar structure to Pim1, should play a central role in the pathogenesis of DM-induced myocardial hypertrophy and HF." (PMID 39850120, 2025).
lupus (2 papers, 2023). "The inhibitor of the serine/threonine kinase Pim-1 “SGI-1776” was identified as a promising therapy, corroborating experimental data which suggest that inhibition of the Pim-1/NFATc1/NLRP3 pathway ameliorates nephritis in lupus mouse models." (PMID 37072752, 2023).
MALT lymphoma (2 papers, 2015 to 2025). An indolent, extranodal type of non-Hodgkin lymphoma composed of small B-lymphocytes (centrocyte-like cells). "Our group reported somatic missense mutations in PIM1 and cMyc in 46% and 30% of MALT lymphomas (gastric and extragastric origin) and in 30% and 41% of transformed MALT lymphomas and 72% of primary cutaneous marginal zone B cell lymphomas (PCMZL), considered as integral part of MALT lymphomas." (PMID 25922601, 2015).
myeloid leukemia (2 papers, 2014 to 2023). A clonal proliferation of myeloid cells and their precursors in the bone marrow, peripheral blood, and spleen. "In some myeloid cells, except neutrophils and monocytes, GM‐CSF and IL‐3 can induce pim‐1 production, suggesting that pim‐1 is an important intermediate in some cytokine‐induced transmembrane signals or responses in myeloid leukemia." (PMID 37162273, 2023). "Transplantation of murine bone marrow co-expressing MYC and PIM1, PIM2 or PIM3 caused rapid and uniformly lethal myeloid leukemia." (PMID 25238262, 2014).
Obesity (2 papers, 2016 to 2018). Accumulation of substantial excess body fat. "It will be interesting to investigate the functional significance and molecular mechanism of PIM1 in different tissues and under different metabolically challenging conditions such as diet induced obesity or cold exposure in vivo, especially the direct targets of this kinase." (PMID 27923061, 2016).
osteoporosis (2 papers, 2025). A condition of reduced bone mass, with decreased cortical thickness and a decrease in the number and size of the trabeculae of cancellous bone (but normal chemical composition), resulting in increased fracture incidence. "To determine whether targeting Pim1 can reduce the excessive osteoclast activity that drives various bone diseases, we treated a murine model of osteoporosis-like disease with the Pim1 kinase inhibitor SGI-1776." (PMID 40164682, 2025).
prostate adenocarcinoma (2 papers, 2014 to 2020). "Our results indicate that PIM-1 is overexpressed at a high frequency in EpCAM(+) CTC fraction in mCRPC (37.5%), when compared to the TCGA data in prostate adenocarcinoma primary tumors (6%)." (PMID 32397108, 2020).
pyelonephritis (2 papers, 2013 to 2014). An inflammatory process affecting the kidney. "In our experiments we observed a clear relationship between the expression of PIM1 transgene and the development of pyelonephritis but appears only in the presence of hormone treatment." (PMID 23565217, 2013). "This hyperplasia may lead to light occlusion of the bladder and urethra because 50% of the animals overexpressing the pim1 transgene developed pyelonephritis and needed to be sacrificed." (PMID 24860787, 2014). "Furthermore, Pim1 overexpression in combination with hormone treatment increased inflammation in the surrounding target tissues, leading to pyelonephritis in the transgenic animals." (PMID 24860787, 2014). "This hypothesis is indirectly supported by the fact that only mice expressing the PIM1 transgene and were subjected to hormone treatment developed inflammation and subsequent pyelonephritis." (PMID 23565217, 2013). "Furthermore, Pim1 overexpression, in combination with the hormone treatment, increased inflammation surrounding target tissues leading to pyelonephritis in transgenic animals." (PMID 23565217, 2013). "The increased inflammation observed in the pim1 transgenic mice after hormone treatment may be due to a positive feedback loop between hormone treatment and pim1 transgene expression because only these mice developed inflammation and subsequent pyelonephritis." (PMID 24860787, 2014).
renal cell carcinoma (2 papers, 2017 to 2021). "In prior studies CDK4/6 and PIM1 have both been shown to be potential targets in renal cell carcinoma, making abemaciclib an attractive therapeutic agent." (PMID 29221116, 2017). "Abemaciclib is a potent CDK4/6 and PIM1 kinase inhibitor, thus we evaluated the effects of abemaciclib on renal cell carcinoma." (PMID 29221116, 2017).
squamous cell carcinoma (2 papers, 2021 to 2022). A carcinoma arising from squamous epithelial cells. "PIM1 expression was examined in 134 NSCLC patients (56 adenocarcinomas, 65 squamous cell carcinomas and 13 of other histology) of various stages (I–IV) by immunohistochemical analysis." (PMID 33946744, 2021).
T-cell acute lymphoblastic leukemia (2 papers, 2019 to 2022). Acute lymphoblastic leukemia of T-cell origin. "In T-cell acute lymphoblastic leukemia (T-ALL), HOXA9 acts as an oncogene by cooperating with JAK3/STAT5 at the transcriptional level through upregulating the expression of downstream genes, such as PIM1 and activator protein-1 (AP-1), thereby affecting cell survival and apoptosis." (PMID 31013831, 2019).
T-cell leukemia (2 papers, 2014 to 2025). A malignant disease of the T-lymphocytes in the bone marrow, thymus, and/or blood. "Our finding of a defective PIM1 expression in a small cohort of aggressive CD8 + T-LGLL supported the reasonableness of our hypothesis, along with the finding of PIM1 down-regulation in another aggressive mature T-cell leukemia, i.e. T-cell prolymphocytic leukemia." (PMID 40721648, 2025). "FACS analysis of four PIM1/MYC mice and one mouse from PIM2, PIM3, and BCLxl cohorts demonstrates only myeloid cell (GR-1 and CD11b) markers, indicating a myeloid, not T-cell leukemia." (PMID 25238262, 2014).
type 1 diabetic (2 papers, 2014 to 2017). "Intriguingly, systemic administration of Pim-1 in STZ-induced type 1 diabetic mice via cardiotropic adeno-associated virus serotype-9 vector or administration of benfotiamine, a vitamin B1 analog at the initial stage halted the progression of the disease." (PMID 24528626, 2014). "We found that significant upregulation of 33-kDa Pim-1 was detected in VSMCs from STZ-induced type I diabetic rat arteries in vivo and HG-treated VSMCs in vitro." (PMID 29179437, 2017). "We have previously reported a blunted activation of VEGFR-2/Akt/Pim-1 pro-survival signaling pathway in STZ-induced type 1 diabetic mice which consequently resulted in increased cardiomyocyte apoptosis, reduced cardiac contractility and neovascularization." (PMID 24528626, 2014).
acute lung injury (1 paper, 2024). A condition of lung damage that is characterized by bilateral pulmonary infiltrates (pulmonary edema) rich in neutrophils, and in the absence of clinical heart failure. "Besides, SIRT6 attenuates LPS-induced inflammation and lung epithelial cell apoptosis in acute lung injury (ALI) by inhibiting angiotensin converting enzyme 2 (ACE2)/STAT3/Pim-1 proto-oncogene, serine/threonine kinase (PIM1) signaling." (PMID 39372420, 2024).
adenoid cystic carcinoma (1 paper, 2014). A malignant tumor arising from the epithelial cells. "However, few studies have concerned the implications of Pim-1 in the salivary gland adenoid cystic carcinoma (ACC)." (PMID 25551195, 2014).
allergic reactions (1 paper, 2024). "Collectively, this evidence suggests that targeting the PIM1/RUNX3 axis may be a novel potential measure for the control of food-induced allergic reactions through the regulation of Th2 and Th17 differentiation." (PMID 39372407, 2024).
anaplastic large cell lymphoma (1 paper, 2019). Anaplastic large cell lymphoma (ALCL) is a rare and aggressive peripheral T-cell non-Hodgkin lymphoma, belonging to the group of CD30-positive lymphoproliferative disorders, which affects lymph nodes and extranodal sites. "Finally, overexpression of PIM1 is similarly found to induce resistance to brigatinib and ceritinib in cell lines derived from ALK-positive anaplastic large cell lymphoma (ALCL)." (PMID 31780656, 2019).
Arterial thrombosis (1 paper, 2024). The formation of a blood clot inside an artery. "We have previously shown the anti-platelet and anti-thrombotic properties of Pim kinase inhibitors and Pim-1 deletion in in vitro and in vivo models of arterial thrombosis." (PMID 39062849, 2024).
Atherosclerotic lesion (1 paper, 2025). A lesion associated with atherosclerosis, a multifactorial and multipart progressive disease manifested by the focal development within the arterial wall of lesions, that ranges from the development of a fatty streak, plaque progression, and plaque disruption. "Using quantitative polymerase chain reaction, western blotting, and immunohistochemistry, we demonstrated that the expression of PIM1 in ox-LDL stimulated endothelial cells and in human and mouse atherosclerotic lesions." (PMID 39744686, 2025).